ALKBH5 (alkB homolog 5, RNA demethylase)
Diseases named in the same sentence as ALKBH5 in open-access papers (continued):
Sharing a sentence is not in itself a finding about the gene and the disease.
osteosarcoma (continued). "Here, we reported that ALKBH5-induced m6A demethylation inhibits human osteosarcoma tumor cell growth, migration, and invasion through m6A-based post-transcriptional regulation of pre-miRNA-181b-1 and an oncogenic transcriptional co-activator Yes-associated protein 1 (YAP)." (PMID 33431791, 2021). "It was also affirmed that ALKBH5 took a great part in contributing to osteosarcoma tumorigenesis." (PMID 32742194, 2020). "Up-regulation of ALKBH5 was found to promote demethylate in osteosarcoma cells and suppress cell proliferation and migration, which suggested that ALKBH5 could serve as a potential therapeutic target for treating human osteosarcoma." (PMID 36072293, 2022). "Thus, ALKBH5 overexpression might be considered a new approach of replacement therapy for osteosarcoma treatment." (PMID 33431791, 2021). "Nevertheless, current research on m6A methylation modifications in osteosarcoma has predominantly focused on METTL3, METTL14, WTAP, ALKBH5, and YTHDF2, with few studies on other m6A methylation regulators." (PMID 40176793, 2025). "Notably, RNA demethylase ALKB Homolog 5 (ALKBH5)-mediated m6A deficiency in osteosarcoma leads to increased expression of USP22 and RNF40, suppressing H2A ubiquitination and promoting gene expression related to replication and DNA repair, driving osteosarcoma progression." (PMID 39048965, 2024). "Taken together, this ALKBH5/PVT1/miR-486/PKC-δ axis significantly induced the malignant progression of osteosarcoma, indicating a novel target in osteosarcoma detection and treatment." (PMID 37069649, 2023). "ALKBH5 can mediate m6A demethylation of lncRNA PVT1 in osteosarcoma, thus upregulating PVT1 and promoting osteosarcoma cell proliferation." (PMID 37151887, 2023). "A recent study reported that ALKBH5 mediates the m6A modification of PVT1 and increases the stability of PVT1 to promote osteosarcoma tumorigenesis." (PMID 36376862, 2022). "Another study found that ALKBH5 mediates the upregulation of PVT1 expression through m6A and promotes the proliferation of osteosarcoma cells." (PMID 35945641, 2022). "To establish the relationship between ALKBH5 and YAP, we further analyzed the effects of cell growth upon co-transfection by two overexpressed plasmids of ALKBH5 and YAP in osteosarcoma cells." (PMID 33431791, 2021). "Meanwhile, immunostaining confirmed a significant decrease of ALKBH5 in U2OS, Saos2, 143B osteosarcoma cell lines, as compared with hOB cells." (PMID 33431791, 2021). "Whereas ALKBH5 silence enhanced m6A methylations of pre-miR-181b-1 and YAP-mRNA exerting oncogenic functions in osteosarcoma." (PMID 33431791, 2021). "Significantly lower ALKBH5 protein expression was detected in malignant osteosarcoma cores especially in the IVB stage, the highest degree of osteosarcoma, compared with normal bone tissues." (PMID 33431791, 2021). "ALKBH5 upregulates the expression of USP22 and RNF40 by regulating the m6A levels of histones, leading to inhibition of H2A monoubiquitination and induction of critical oncogenes, ultimately promoting osteosarcoma progression." (PMID 39062505, 2024). "The aberrant downregulation of the demethylase ALKBH5 (ALKB homolog 5) in osteosarcoma leads to the upregulated expression of YAP, consequently enhancing the proliferation, invasion, and metastatic ability of osteosarcoma cells." (PMID 38202722, 2023). "In osteosarcoma, Yuan and co-workers discovered downregulated levels of ALKBH5 in osteosarcoma cell/tissue specimens in comparison with noncancerous osteoblast cell/tissue samples, which was contrary to the observation of a previous study." (PMID 35063010, 2022). "In another study on osteosarcoma, ALKBH5 was also found to inhibit the occurrence and development of tumors through m6A-dependent epigenetic silencing of the pre-miR-181b-1/YAP signal axis present in osteosarcoma." (PMID 34149432, 2021).
osteosarcoma (continued). "Another investigation revealed that m6A demethylase ALKBH5 could suppress the degradation of lncRNA PVT1, and its overexpression promoted osteosarcoma cell proliferation in vitro and tumor growth in vivo." (PMID 32982586, 2020). "Moreover, there was a significant decrease in demethylase ALKBH5 mRNA inversely correlated with m6A contents in all three osteosarcoma cell lines as compared with hOB cells, but not in METTL3, METTL14, WTAP, and FTO." (PMID 33431791, 2021).
lung carcinoma (48 papers, 2018 to 2025). "Recent studies have shown that ALKBH5 is specifically upregulated in lung cancer tissues, and its expression is strongly associated with poor prognosis and infiltration of PD-L1+ TAMs." (PMID 41562066, 2025). "Kaplan–Meier analysis showed that increased ALKBH5 expression was associated with shorter overall survival in patients with lung cancer." (PMID 38872221, 2024). "This suggests that ALKBH5 is upregulated in lung cancer and is associated with poor prognosis in lung cancer patients." (PMID 38166832, 2024). "To investigate the effect of both CDKN1A in PC9 and TIMP3 in A549 on cell proliferation in ALKBH5-deficient lung cancer cell lines, we confirmed the reduced expression using siRNA." (PMID 35318440, 2022). "We then identified that ALKBH5 was upregulated in lung cancer tissues and associated with poor prognosis of lung cancer patients by analyzing a public database." (PMID 36376862, 2022). "In this study, we identified the m6A demethylase ALKBH5 using a public database of lung cancer tissues, and found that it was highly associated with poor overall survival of lung cancer patients." (PMID 36376862, 2022). "Bioinformatics analysis showed that ALKBH5 was upregulated in lung cancer tissues, and high expression levels of ALKBH5 were associated with poor prognosis in lung cancer patients." (PMID 36376862, 2022). "However, increasing evidence suggests that m6A demethylases FTO and ALKBH5 are frequently overexpressed in lung cancer and significantly associated with the tumor’s prognosis." (PMID 38094306, 2023). "To investigate whether LKB1 loss affects ALKBH5 and m6A modification, we screened several lung cancer cell lines and categorized them based on KRAS mutation and LKB1 expression status." (PMID 34016959, 2021). "This study also represents the instance of a mutant KRAS oncogene hijacking the ALKBH5 PTMs/m6A methylation–mediated DNA damage response pathway to confer resistance to cytotoxic drugs in lung cancer cells." (PMID 39960727, 2025). "For example, evaluating the expression level of ALKBH5 in blood or tissue samples from lung cancer patients has the potential to contribute to early diagnosis, pathological classification, and staging of lung cancer patients." (PMID 40958857, 2025). "For instance, in lung cancer, ALKBH5 counteracts YTHDF2-mediated degradation of Sox2 and thereby promoting tumor aggressiveness." (PMID 39098905, 2024). "In lung cancer, patients with high expression of ALKBH5 have shorter overall survival (OS) than those with low expression of ALKBH5." (PMID 38166832, 2024). "The inhibitory effect of anti-PD-L1 therapy on tumor growth was attenuated in ALKBH5-knockdown mice, suggesting that lung cancer cells with high ALKBH5 expression are more sensitive to anti-PD-L1 therapy." (PMID 38872221, 2024). "Increased ALKBH5 expression confers increased sensitivity to anti-PD-L1 therapy in lung cancer cells." (PMID 38872221, 2024). "Overexpression of PVT1 partially recuperates the lung cancer angiogenesis constrained by ALKBH5 knockdown through mediating VEGFA expression." (PMID 39691597, 2024). "In lung cancer patients, the levels of ALKBH5 protein expression have been observed to be positively associated with tumor size, TNM staging, and clinical staging." (PMID 38094306, 2023). "It has been confirmed that RNA methyltransferases such as WTAP and METTL3 and RNA demethylases such as ALKBH5 and FTO are intimately associated with destructive lung diseases, including different types of lung cancer." (PMID 37936118, 2023). "Recent studies have highlighted the importance of FTO and ALKBH5, as erasers involved in m6A RNA demethylation, in the development of lung cancer." (PMID 38094306, 2023).
lung carcinoma (continued). "YTHDF1 promotes lung cancer progression through its involvement in the m6A demethylase ALKBH5 pathway." (PMID 36733344, 2023). "The conditioned media of A549 or H1975 cells transfected with si-ALKBH5 or NC was collected to treat HUVECs, and we found that tube formation was inhibited when ALKBH5 was silenced in the two lung cancer cell lines." (PMID 36376862, 2022). "We observed that ALKBH5 promoted the proliferation and metastasis of lung cancer cells in vitro and in vivo." (PMID 36376862, 2022). "In summary, we demonstrated the oncogenic roles of ALKBH5 in lung cancer cells in vitro and in vivo." (PMID 36376862, 2022). "Overexpression of PVT1 partially restored the proliferation, migration and angiogenesis suppressed by ALKBH5 knockdown in lung cancer." (PMID 36376862, 2022). "For example, METTL3 is upregulated in lung cancer and required for tumor growth, invasion, survival and progression, while ALKBH5 has the opposite effects." (PMID 35078505, 2022). "After elucidating the critical roles of Mettl3 and ALKBH5 in mice and murine lung cancer cells, we next evaluated their functions in human LUAD cells." (PMID 35078505, 2022). "In recent years, ALKBH5 has been shown to play oncogenic roles in lung cancer, but the mechanism still needs to be studied further." (PMID 36376862, 2022). "The results of zebrafish xenograft models of lung cancers showed that silencing ALKBH5 inhibited the proliferation and metastasis of A549 cells in vivo." (PMID 36376862, 2022). "To study the function of m6A-related genes in lung cancer, we chose ALKBH5, which is one of the two m6A mRNA demethylases." (PMID 36376862, 2022). "Next, a Kaplan‒Meier analysis revealed that lung cancer patients with high expression levels of ALKBH5 had shorter overall survival (OS) than those with low expression levels of ALKBH5." (PMID 36376862, 2022). "Synergized suppression of intra-pulmonary tumor formation was observed upon knocking out Mettl3 and overexpressing ALKBH5 simultaneously, indicating that Mettl3 and ALKBH5 are critical for maintaining transformative phenotypes in murine lung cancer cells." (PMID 35078505, 2022). "Zebrafish lung cancer xenografts showed that ALKBH5 silencing also suppressed the growth and metastasis of lung cancer cells." (PMID 36376862, 2022). "Collectively, the specific mechanisms of ALKBH5 in lung cancer still need to be explored in future studies." (PMID 35628623, 2022). "Western blot analysis demonstrated that ALKBH5 was endogenously expressed in all lung cancer cell lines and FTO was expressed in almost all lung cancer cell lines except HLC-1." (PMID 35318440, 2022). "A growing number of studies have demonstrated that ALKBH5 is involved in various diseases, such as lung cancer." (PMID 35279083, 2022). "Taken together, these results suggest that silencing ALKBH5 decreased the expression level of PVT1 by regulating its stability in lung cancer cells." (PMID 36376862, 2022). "To study the biological functions of ALKBH5 in lung cancer cells, we first transfected ALKBH5 siRNAs or NC siRNA into A549 and H1975 cells to silence ALKBH5." (PMID 36376862, 2022). "To study the mechanism of ALKBH5 in tumor angiogenesis in lung cancer cells, we first analyzed the potential m6A modification sites of VEGFA mRNA." (PMID 36376862, 2022). "To identify downstream targets of ALKBH5-mediated m6A modification in lung cancer, we overlapped 2605 genes using the canonical m6A motif-enriched gene stop codon region based on m6A-sequence in A549 cells." (PMID 34016959, 2021). "Consistent with previous studies, our observations indicate that ALKBH5 is a lung cancer oncogene because it promoted cell proliferation and migration." (PMID 34016959, 2021).
lung carcinoma (continued). "Next, we explored functional relationships between LKB1 and ALKBH5 in KRAS mutant lung cancer cells." (PMID 34016959, 2021). "We found that ALKBH5 is highly expressed in lung cancer cells, and more, Alkbh5 knockout significantly decreased UBE2C expression in NSCLC." (PMID 29904125, 2018). "Down-regulation of ALKBH5 inhibits the angiogenesis of lung cancer cells in vitro and in vivo." (PMID 38166832, 2024). "A recent publication found ALKBH5 can facilitate the advancement and angiogenesis of lung cancer by modulating the stability of the long non-coding RNA (LncRNA) PVT132, and PVT1 was also reported highly upregulated in GBM tissues and cells, and involved in GBM malignant progression." (PMID 38221546, 2024). "Additionally, ALKBH5 has been reported to facilitate Sox2 expression in lung cancer, MM and endometrial cancer." (PMID 39098905, 2024). "Furthermore, we will discuss future directions of research in this field and explore the potential clinical applications of targeting of FTO and ALKBH5 in the treatment of lung cancer." (PMID 38094306, 2023). "FTO and ALKBH5 are known to be upregulated in lung cancer tissues." (PMID 38094306, 2023). "Knockdown of ALKBH5 inhibited the proliferation and migration of cultured lung cancer cell lines." (PMID 36376862, 2022). "Our study revealed for the first time that ALKBH5 is required for the angiogenesis of lung cancer." (PMID 36376862, 2022). "In contrast to the results that ALKBH5 positively regulated VEGFA expression in lung cancer cells, the mRNA stability data suggested that there may be a regulatory mediator between ALKBH5 and VEGFA." (PMID 36376862, 2022). "The two studies also showed YTHDF2 could recognize m6A-modified sites of lncRNA KCNQ1OT1 or PVT1 and regulate their stability, but whether ALKBH5 regulates the stability of PVT1 via YTHDF2 in lung cancer cells remains to be examined further." (PMID 36376862, 2022). "Finally, rescue experiments revealed that ALKBH5 regulated the proliferation, migration and angiogenesis of lung cancer cells, partially through PVT1." (PMID 36376862, 2022). "We found that ALKBH5 was highly expressed in lung cancer tissues compared with normal tissues." (PMID 36376862, 2022). "To determine whether ALKBH5 mediates the m6A modification of PVT1 in lung cancer cells, we carried out RNA immunoprecipitation (RIP) assays which revealed that ALKBH5 bounded directly to PVT1 in A549 cells." (PMID 36376862, 2022). "A zebrafish lung cancer xenograft model was used to verify the function of ALKBH5 and PVT1 in vivo." (PMID 36376862, 2022). "We also found that ALKBH5 regulated the angiogenesis of lung cancer in vitro and in vivo." (PMID 36376862, 2022). "Consequently, qPCR analysis demonstrated that ALKBH5 mRNA expression was higher in lung cancer cell lines except for LC-2/ad and RERF-LC–MS, whereas FTO mRNA expression was lower in lung cancer cell lines except for HLC-1, ABC1, and PC3." (PMID 35318440, 2022). "Thus, we examined the relationship between ALKBH5 and PVT1 in lung cancer and found that knockdown of ALKBH5 decreased the expression levels of PVT1 in A549 and H1975 cells." (PMID 36376862, 2022). "Similarly, ALKBH5 contributes to lung cancer cell proliferation and metastasis following intermittent hypoxia by inducing the expression of FOXM1 protein in an m6A-dependent manner." (PMID 34491904, 2021). "Additionally, ALKBH5 had the highest basal mRNA expression in human and mouse lung cancer tissues and cell lines." (PMID 34016959, 2021). "Notably, LKB1 regulation of ALKBH5 via 5mC-DNA was not limited to KRAS mutant lung cancer, but extended to pancreatic and colorectal cancer, which are the top three causes of cancer death in the United States34." (PMID 34016959, 2021).